Y_RNA (Y RNA )
Gene: Miscellaneous RNA gene on chromosome 5 (16,623,004 to 16,623,095, reverse strand). Ensembl gene ENSG00000201370.
Homologues: Orthologues: chimpanzee Y_RNA (99% identical), macaque Y_RNA (83% identical). Paralogues in human: RNY1 (89% identical), Y_RNA (88% identical), Y_RNA (87% identical), Y_RNA (86% identical), Y_RNA (85% identical), RNY1P11 (84% identical), RNY1P13 (84% identical), RNY1P8 (84% identical), Y_RNA (84% identical), RNY1P10 (83% identical), RNY1P7 (83% identical), Y_RNA (83% identical), and 97 more.